IGKJ5 (immunoglobulin kappa joining 5)
Synonyms: J5
Gene: Immunoglobulin joining (J) gene on chromosome 2 (88,860,568 to 88,860,605, reverse strand). Ensembl gene ENSG00000211593.
Diseases named in the same sentence as IGKJ5 in open-access papers:
IGKJ5 is named in the same sentence as 1 disease in open-access papers, as found by Europe PMC text mining. Sharing a sentence is not in itself a finding about the gene and the disease.
IGKJ5 shares sentences with these, for which no sentence is quoted: tumor (1 paper).